TSPAN3 (tetraspanin 3)
Description:
Regulates the proliferation and migration of oligodendrocytes, a process essential for normal myelination and repair.
Synonyms: Tspan-3; TM4SF8; TM4-A
Tractability: Antibody: UniProt predicts a signal peptide or a membrane-spanning region; its Gene Ontology location is reachable by antibodies, with medium confidence. PROTAC: ubiquitination databases record sites on it; its protein half-life has been measured.
Gene: Protein-coding gene on chromosome 15 (77,041,404 to 77,083,984, reverse strand). Ensembl gene ENSG00000140391.
Subcellular location: Membrane
Subcellular location (Human Protein Atlas): Golgi apparatus; Nucleoplasm
Gene Ontology:
Cellular component: extracellular exosome; plasma membrane; membrane
Genetic constraint (gnomAD): Loss-of-function variants: 8 observed, 20.36 expected, observed/expected ratio (o/e) 0.39, 90% interval 0.23 to 0.71. The upper end of that interval is the gene's LOEUF score, 0.71, which puts it in group 2 of 6, group 1 being the genes least tolerant of losing a copy. Missense variants: 206 observed, 250.19 expected, observed/expected ratio (o/e) 0.82, 90% interval 0.73 to 0.92. Synonymous variants: 116 observed, 93.17 expected, observed/expected ratio (o/e) 1.25, 90% interval 1.07 to 1.45.
Homologues: Orthologues: chimpanzee TSPAN3 (100% identical), dog TSPAN3 (98% identical), pig TSPAN3 (98% identical), mouse Tspan3 (97% identical), rat Tspan3 (97% identical), macaque TSPAN3 (93% identical), guinea pig TSPAN3 (91% identical), zebrafish tspan3a (87% identical), tropical clawed frog tspan3 (84% identical), zebrafish tspan3b (77% identical). Paralogues in human: CD63 (28% identical), TSPAN33 (28% identical), TSPAN7 (25% identical), CD151 (25% identical), TSPAN4 (25% identical), CD82 (23% identical), TSPAN1 (23% identical), TSPAN14 (23% identical), CD37 (23% identical), CD53 (23% identical), TSPAN17 (23% identical), TSPAN9 (23% identical), and 20 more.
Diseases named in the same sentence as TSPAN3 in open-access papers:
TSPAN3 is named in the same sentence as 14 diseases in open-access papers, as found by Europe PMC text mining. Sharing a sentence is not in itself a finding about the gene and the disease. The quoted sentences say what the papers report.
acute myelocytic leukemia (2 papers, 2022 to 2023). "In addition, TSPAN3 knockout impaired leukemia stem cell self-renewal and disease propagation, and significantly improved survival in mouse models of acute myelocytic leukemia." (PMID 36941633, 2023). "Moreover, TSPAN3 is up-regulated in adriamycin-resistant acute myeloid leukemia samples and cells." (PMID 36941633, 2023). "TSPAN3 is known to mediate signal transduction events that regulate the expression of the A disintegrin and metalloproteinase 10 (ADAM10), presenilin and the amyloid precursor protein and the development and progression of acute myelogenous leukemia (AML)." (PMID 35326428, 2022).
leukemia (2 papers, 2022). A malignant (clonal) hematologic disorder, involving hematopoietic stem cells and characterized by the presence of primitive or atypical myeloid or lymphoid cells in the bone marrow and the blood. "Mice with disruption of Tspan3 displayed impaired leukemia stem cell self-renewal and disease propagation and markedly improved survival in mouse models of AML by a mechanism through which the response to CXCL12/SDF-f signal pathway is disabled." (PMID 35326428, 2022). "Other miR-139 targets that are described in leukemia and some other types of cancer are BTG3, the RNA-binding protein ELAVL1, Tetraspanin-3 (TSPAN3), MAX Network Transcriptional Repressor (MNT), 15-Hydroxyprostaglandin Dehydrogenase (HPGD) and Protein Tyrosine phosphatase Receptor Type-T (PTPRT)." (PMID 35269391, 2022).
desmoid tumor (1 paper, 2017). A desmoid tumor (DT) is a benign, locally invasive soft tissue tumor associated with a high recurrence rate but with no metastatic potential. "Therefore, over-expression of miR-21-3p and down-expression of miR-197-3p targeting L1CAM, SERPINA3 and TSPAN3, respectively, could induce or maintain the inflammatory process in mutated desmoid tumor." (PMID 28418912, 2017).
glioma (1 paper, 2023). A benign or malignant brain and spinal cord tumor that arises from glial cells (astrocytes, oligodendrocytes, ependymal cells). "The expression levels of TSPAN3/4/6/11/18/24/25/26/29/30 were significantly correlated with the OS of patients with glioma (p < 0.05)." (PMID 37587203, 2023). "Specifically, the higher the TSPAN3/11 level, the greater the probability of survival in patients with glioma." (PMID 37587203, 2023). "Thus, TSPAN3/11 may play a protective prognostic role, whereas TSPAN4/6/18/24/25/26/29/30 are poor prognostic factors, demonstrating that they may be potential biomarkers for glioma and serve as predictive signals for different prognoses." (PMID 37587203, 2023). "However, studies on the role of TSPAN3/11 in glioma are lacking." (PMID 37587203, 2023).
lung carcinoma (1 paper, 2024). "Baseline expression of TSPAN3 was also examined in six human lung cancer cell lines along with HET293T and HBE cell lines." (PMID 39333841, 2024). "TSPAN3 was found to be highly expressed in lung cancer cells and tissues." (PMID 39333841, 2024). "Furthermore, these findings suggest that TSPAN3 is a potential target for drug development in lung cancer." (PMID 39333841, 2024). "TSPAN3 levels were consistently higher in all six lung cancer cells than those in HBE cells." (PMID 39333841, 2024).
metastatic tumor (1 paper, 2024). "Significant gene upregulation of these tetraspanins (CD53, ROM1, TSPAN3, TSPAN12, TSPAN15, and UPK1B) within immune cells in metastatic tumor suggests their potential involvement in the influence of immune responses." (PMID 38255741, 2024).
neuroblastoma (1 paper, 2022). Neuroblastoma (NB) is the most common solid, extracranial childhood tumor. "It is known that the expression of Tspan 5 and 7 could compensate for the functional loss of TSPAN3 in neuroblastoma cells and in the brains of TSPAN3-decient mice." (PMID 35326428, 2022).
non-small cell lung carcinoma (1 paper, 2024). A group of at least three distinct histological types of lung cancer, including non-small cell squamous cell carcinoma, adenocarcinoma, and large cell carcinoma. "This study aims to explore TSPAN3 expression and clinicopathological significance in non-small cell lung carcinoma (NSCLC) to determine its potential role in cancer progression." (PMID 39333841, 2024).
tumor (9 papers, 2017 to 2025). "Tumor volume and weight in the TSPAN3-overexpressing group were significantly higher than those in control group." (PMID 39333841, 2024). "Moreover, high levels of TSPAN3 positively correlated with poor differentiation, lymph node involvement, advanced pathological tumor-node-metastasis stage, and poor prognosis in patients with NSCLC." (PMID 39333841, 2024). "Furthermore, high levels of TSPAN3 positively correlated with poor differentiation, lymph node involvement, advanced pathological tumor-metastasis-node stage, and poor prognosis among patients with NSCLC." (PMID 39333841, 2024). "TSPAN3 is moderately expressed in normal tissues but highly expressed in tumor tissues." (PMID 37587203, 2023). "CD9, CD151, TSPAN1, TSPAN3, TSPAN8, and TSPAN13 displayed specific overexpression in the tumor compartment, indicating potential roles in tumor growth." (PMID 38255741, 2024). "In the tumor compartment, several tetraspanins (CD9, CD151, TSPAN1, TSPAN3, TSPAN8, and TSPAN13) were specifically overexpressed, suggesting their involvement in tumor growth and proliferation in stage 4 primary CC." (PMID 38255741, 2024). "All processes involved in tumor neo-angiogenesis, and the mechanisms of action in tumor cell proliferation, involve the ACVR1 and TSPAN3 genes, which are target genes for miR-197 and the IGFBP5 receptor." (PMID 36143221, 2022). "We found that the L1CAM, TSPAN3 and SERPINA3 gene expression were significantly up-regulated in M than Wt sporadic tumor samples, whereas COL1A1 and MAT2A mRNA showed similar levels in both groups." (PMID 28418912, 2017). "We further investigated contexts of these spMOCA’s hub genes, where we identified specific prognostic genes serves as hub genes in the same tumor type, for example, WIPF2 and CASC3 for BRCA, COX6A1 and PRAP1 for CRC, E2F1 and AKR1C3 for LUSC, and TSPAN3 and SLC4A11 for OVCA." (PMID 41370198, 2025).
cancer (4 papers, 2022 to 2024). A tumor composed of atypical neoplastic, often pleomorphic cells that invade other tissues. "Tissue samples from patients diagnosed with NSCLC were analyzed by immunohistochemistry, western blotting, and real-time polymerase chain reaction (PCR) to indicate the involvement of TSPAN3 in cancer progression." (PMID 39333841, 2024). "The mRNA expression of TSPAN3/4/6/11/12/18/24/25/26/29/30 was significantly correlated with the individual cancer grades (p < 0.05)." (PMID 37587203, 2023). "TSPAN1, TSPAN3, TSPAN12, TSPAN31, CD82 and CD63 have also been reported to reduce chemosensitivity of cancer cells." (PMID 36941633, 2023). "The following TSPANs have been involved in enhancing cancer therapy resistance: CD9, CD81, TSPAN1, TSPAN3, TSPAN31, CD82 and CD63." (PMID 36941633, 2023).
infection (1 paper, 2022). The state of being infected such as from the introduction of a foreign agent such as serum, vaccine, antigenic substance or organism. "Especially, blocking the activity of large extracellular loop domain of Fenneropenaeus chinensis tetraspanin-3 by anti-LEL antibody significantly inhibit the infection of white spot syndrome virus in Chinese shrimp." (PMID 35310653, 2022).
TSPAN3 also shares sentences with these, for which no sentence is quoted: cholangiocarcinoma (1 paper); GM2 gangliosidosis (1); lymph node metastases (1).